SOX7 (SRY-box transcription factor 7)
Diseases named in the same sentence as SOX7 in open-access papers (continued):
Sharing a sentence is not in itself a finding about the gene and the disease.
cancer (36 papers, 2009 to 2025). A tumor composed of atypical neoplastic, often pleomorphic cells that invade other tissues. "It has also been shown that a loss of SOX7 expression results in acquiring a drug-resistant phenotype against many chemotherapeutic agents by cancer cells." (PMID 33152990, 2020). "A decreased expression of Sox7 determined by quantitative real-time reverse transcription polymerase chain reaction (qRT-PCR) and/or IHC in lung AC, has demonstrated to be associated with poor differentiation of cancer cells and a better overall survival rate." (PMID 23443092, 2012). "Afterward, the variance in SOX7 transcription level in 25 pairs of cancer and normal bladder tissues was verified by qPCR, revealing a statistically significant reduction in the expression of SOX7 mRNA in BCa tissues." (PMID 39227479, 2024). "Despite the fact that the molecular mechanisms of miR-184/SOX7 interaction require further study, it has been proved that the SOX7 protein is essential to cancer cells for increasing their proliferation abilities." (PMID 33152990, 2020). "In colon, prostate and NSCLC cancer cell lines, overexpression of the SOX7 gene leads to the inhibition of proliferation and colony formation processes, as well as apoptosis induction." (PMID 33152990, 2020). "For the two SOX7-repressed genes, previous studies suggested their proliferative roles in cancer development." (PMID 29757932, 2018). "The SOX7 gene is located on the p arm of human chromosome 8 at a locus frequently deleted in cancers; however, SOX7 homozygous deletions are rare in cancers based on available SOX7-related literature." (PMID 29757932, 2018). "Overall, we identified multiple cancer-related pathways mediated by SOX7 and for the first time revealed SOX7-regulated target genes in a cancer-relevant context." (PMID 29757932, 2018). "MiR-452-5P was up-regulated and predicted poor patient survival and advanced TNM stage in HCC patients, and miR-452 was identified to promote cancer stem cells by inhibiting Sox7 through activating Wnt/β-Catenin signaling pathway." (PMID 28969024, 2017). "On the other hand, reports are also available to show that SOX7 mRNA is significantly up-regulated in cancer, such as in pancreatic, gastric, and esophageal cancer cell lines, as well as in primary gastric cancer." (PMID 25297608, 2014). "There are also contradicting reports to demonstrate that SOX7 mRNA was significantly up-regulated in several human cancer cells." (PMID 25297608, 2014). "On the other hand, a downregulated expression of Sox7 in lung adenocarcinoma was a poor prognosis marker for patients with this type of cancer." (PMID 23443092, 2012). "FZD8, WIF1 and SOX7 were identified by HTself as differentially expressed between cancer and luminal cells, and in whole tissue CP compared to NP." (PMID 20021671, 2009). "Furthermore, the anti-cancer properties of SOX7 have been discovered through its ability to suppress the Wnt/β-catenin signaling pathway." (PMID 40230854, 2025). "The reason of SOX7-induced apoptosis in various cancer types may be owing to its activation of the MAPK/ERK-BIM apoptotic signaling pathway." (PMID 40699642, 2025). "When delving into the mechanism underlying SOX7 and cancer development, ample evidence supports the direct interaction of SOX7 with β-catenin binding, thereby facilitating the negative regulation of Wnt/β-catenin signaling to modulate cell growth." (PMID 39227479, 2024). "This indicates that in addition to Wnt signaling transduction, SOX7 may also participate in the regulation of other pathways related to cancer." (PMID 39227479, 2024). "For example, it is proved that SOX7 is a suppressive target gene expressed in the NSCLC cells and the forced expression of SOX7 in NSCLC cell lines could markedly reduce the cancer cell growth and enhanced their apoptosis." (PMID 33506873, 2021).
cancer (continued). "Moreover, similar to SHP2 and SOX7, the conditioned media obtained from culturing cancer cells induced c-Jun expression and activation." (PMID 34728626, 2021). "Similar to SHP2, conditioned media obtained from the cancer cell culture induced SOX7 expression." (PMID 34728626, 2021). "Emerging studies have suggested that SOX7 is downregulated in several human cancers." (PMID 29029454, 2017). "Increasing lines of evidence have shown that SOX7 may play pivotal roles in multiple cancers via regulating the activity of Wnt/β-catenin signaling pathway." (PMID 29029454, 2017). "SOX7 was previously reported as a tumor suppressor in various cancers." (PMID 24558429, 2014). "In cancer cell lines, overexpression of SOX7 blocks β-catenin-mediated transcriptional activity." (PMID 24816720, 2014). "Emerging reports have documented that Sox7 is down-regulated in several human cancers and may be a negative regulator of Wnt/β-catenin signaling activity." (PMID 23295859, 2012). "In NSCLC, miR-21 is a serum biomarker for detection of early-stage NSCLC, and has been found to enhance cancer progression by targeting its targets genes, like SOCS1, PTEN, SOX7." (PMID 33081752, 2020). "To our knowledge, we for the first time report here the relationships between SOX7 and Smad7 and open the opportunity to elucidate the role of Smad7 in relation to SOX7 or other SOX members in cancers." (PMID 27188720, 2016). "Of the 13 recurrently underexpressed SOX genes, SOX3, SOX5, SOX7 and SOX10 were exclusively underexpressed (i.e. they showed overexpression frequencies <20% in all cancer types)." (PMID 25594027, 2014). "Importantly, the SOXF proteins, namely SOX7, SOX17 and SOX18, were validated to play important roles in cell fate determination and multiple cancer types." (PMID 40778650, 2025). "IWR-1 had been proved to be a potent inhibitor of WNT/β-catenin pathway in a variety of cancer cells.We found that the expression of SOX7 was not changed in A549-Control and H1299-Control cells after treatment with IWR-1 by qRT-PCR and Western blot assays." (PMID 39346732, 2024). "Notably, 17 TFs among the X-linked male-amplifiers exhibited motif enrichment across more than two cancer types, including AP-1, E2F1, and Sox7." (PMID 39716176, 2024). "Furthermore, SOX7 and SOX17 have been demonstrated to possess antiproliferative functions in cancer cells." (PMID 37511076, 2023). "The SOXF family (SOX7, SOX17 and SOX18) plays a crucial role in angiogenesis or lymphangiogenesis, and SOX18 has been shown to be a potential target for antiangiogenic therapy in cancer." (PMID 32363730, 2020). "Currently reported effects of SOX7 on its direct target genes are activation, although not studied in a cancer-relevant context." (PMID 29757932, 2018). "When RNA-seq expression levels of 29 MM cell lines from the Cancer Cell Line Encyclopedia were visually analyzed in the Expression Atlas database, we observed that 25 of 29 (86.2%) MM cell lines did not have SOX7 transcript expression, whereas other MM cell lines also had quite low expression." (PMID 40699642, 2025). "However, whether SOX7 as a transcription factor regulates any cancer-related gene or signaling pathway has never been reported, and our evidence to date suggests that a thorough investigation would be timely." (PMID 29757932, 2018). "In the cancer cells as well as cancer cell lines (data not shown), there was increased expression of Wnt receptor FZD8; decreased expression of Wnt inhibitor WIF1, which functions to sequester Wnt molecules from receptor binding, and that of the transcription factor SOX7." (PMID 20021671, 2009).
heart diseases (1 paper, 2013). "Our study suggests that the loss of REPD or nearby regions may raise the risk of heart diseases by impacting the following genes, such as SOX7." (PMID 24009689, 2013).
SOX7 also shares sentences with these, for which no sentence is quoted: developmental delay (3 papers); Intellectual disability (3); adenocarcinoma (2); lung (2); Pancreatic Cancer (2); acute leukemia (1); asthma (1); autism spectrum disorder (1); campomelic dysplasia (1); cardiovascular disease (1); Cerebral ischemia (1); cervical cancer (1); chronic leukemia (1); chronic myelogenous leukemia (1); clear-cell renal-cell carcinoma (1); colon adenocarcinoma (1); colorectal tumors (1); dysplasia (1); endometrioid carcinoma (1); hematological malignancies (1); high-grade glioma (1); lung tumor (1); metastatic tumors (1); mucinous cystadenocarcinoma (1); Multiple Myeloma (1); nasopharyngeal carcinoma (1); ovarian endometrioid carcinoma (1); pituitary adenoma (1); renal carcinoma (1); renal cell carcinoma (1).
A further 6 diseases each share a sentence with SOX7 in 1 paper.